ZNG1A (Zn regulated GTPase metalloprotein activator 1A)
Description:
Zinc chaperone that directly transfers zinc cofactor to target metalloproteins, thereby activating them. Catalyzes zinc insertion into the active site of methionine aminopeptidase METAP1, which function to cleave the initiator methionine from polypeptides during or after protein translation. Mechanistically, the N-terminal psi-PxLVp motif binds to the C6H2-type zinc finger of inactive form of METAP1. After formation of the docked complex, zinc is transferred from the CXCC motif in the GTPase domain of ZNG1A to the zinc binding site in the peptidase domain of METAP1 in a process requiring GTP hydrolysis. GTP/GDP exchange is required for release of active METAP1.
Synonyms: CBWD1; COBP
Tractability: Antibody: the Human Protein Atlas places it where antibodies can reach. PROTAC: ubiquitination databases record sites on it.
Gene: Protein-coding gene on chromosome 9 (119,288 to 179,147, reverse strand). Ensembl gene ENSG00000172785.
Subcellular location: Nucleus
Subcellular location (Human Protein Atlas): Plasma membrane
Gene Ontology:
Molecular function: protein binding; GTPase activity; zinc chaperone activity; zinc ion binding
Biological process: kidney development; protein maturation
Cellular component: nucleus
Genetic constraint (gnomAD): Loss-of-function variants: 8 observed, 21.93 expected, observed/expected ratio (o/e) 0.36, 90% interval 0.21 to 0.66. The synonymous counts are far from expectation, so gnomAD's model fits this gene poorly and the ratio says little. Missense variants: 124 observed, 193.47 expected, observed/expected ratio (o/e) 0.64, 90% interval 0.55 to 0.74. Synonymous variants: 45 observed, 69.21 expected, observed/expected ratio (o/e) 0.65, 90% interval 0.51 to 0.83.
Homologues: Paralogues in human: ZNG1B (98% identical), ZNG1C (98% identical), ZNG1E (98% identical), ZNG1F (97% identical).
Diseases named in the same sentence as ZNG1A in open-access papers:
ZNG1A is named in the same sentence as 7 diseases in open-access papers, as found by Europe PMC text mining. Sharing a sentence is not in itself a finding about the gene and the disease.
ZNG1A shares sentences with these, for which no sentence is quoted: breast carcinoma (1 paper); cancer (1); melanoma (1); ovarian carcinoma (1); renal hypoplasia (1); tumor (1); Varicose veins (1).